TCF7L2 (transcription factor 7 like 2)
Diseases named in the same sentence as TCF7L2 in open-access papers (continued):
Sharing a sentence is not in itself a finding about the gene and the disease.
adenoma (8 papers, 2010 to 2025). A neoplasm arising from the epithelium. "Interestingly, the authors found two TCF7L2-adenoma-specific mutations." (PMID 33923068, 2021). "Perhaps, because of functional redundancy between members of Tcf/Lef family, we detected compensatory increase in Tcf7 or Tcf7l2 transcripts in the Lef1 deleted adenoma cells." (PMID 34788095, 2021). "Mutations in the Wnt-related genes CTNNB1, EP300, TCF7L2, and the AMER1 genes were also observed, but at a lower frequency, in accordance with previous data on adenomas with high grade dysplasia." (PMID 33923068, 2021). "As expected, we found that APC was the most frequently mutated gene across the adenomas studied, while other WNT pathway genes (CTNNB1, EP300, TCF7L2, and AMER1) were altered less frequently." (PMID 31781186, 2019). "We observed that TCF7L2 mutations (one splicing and one frameshift indel) were adenoma-specific, so the oncogenic roles of TCF7L2 mutations may not be related to malignant transformation." (PMID 32023847, 2020).
Anxiety (8 papers, 2011 to 2024). Intense feelings of nervousness, tension, or panic often arise in response to interpersonal stresses. "Several experiments tentatively implicated TCF7L2 deficiency in anxiety and depression." (PMID 31218672, 2019). "We then evaluated the effects of LHb neuron-specific knockdown of TCF7L2 on anxiety, learning, memory, and social behavior." (PMID 39596468, 2024). "Next, we evaluated the effects of LHb neuron-specific overexpression of TCF7L2 on anxiety, learning, memory, and social behavior." (PMID 39596468, 2024). "Even less is known about the relationship between TCF7L2 and psychopathologies, except that Tcf7l2 haploinsufficient mice show anxiety-like behavior and altered fear learning." (PMID 25963709, 2016). "Using the open field and light dark box tests, we observed anxiety-like phenotypes in Tcf7l2+/− mice; ablation of Tcf7l2 led to decreased time in the center of the arena and in the light compartment." (PMID 22046400, 2011). "Taken together, these observations support a role for Tcf7l2 in anxiety-like behaviors; future studies of the impact of human alleles of TCF7L2 on anxiety are warranted." (PMID 22046400, 2011). "Moreover, transgenic mice have revealed a dose-dependent role of Tcf7l2 in fear-conditioning and anxiety, traits for which A/J is known to significantly differ from C57BL/6J." (PMID 34503558, 2021). "While our study uncovered a role for Tcf7l2 on anxiety and fear learning, we did not identify significant differences in PPI in both heterozygous null mice and BAC transgenic mice." (PMID 22046400, 2011). "Notably, the knockdown or overexpression of TCF7L2 did not affect anxiety, learning, memory, or social behaviors, indicating a specific role for TCF7L2 in depression." (PMID 39596468, 2024).
atherosclerosis (8 papers, 2008 to 2025). A disease characterized by the build-up of fatty material and calcium deposition in the arterial wall resulting in partial or complete occlusion of the arterial lumen. "TCF7L2 has been associated with inflammation, metabolic regulation, and the development of atherosclerosis." (PMID 40303486, 2025). "Currently, TCF7L2 has drawn increasing academic attention because it has been reported to be associated with inflammation, metabolism, and atherosclerosis." (PMID 34568447, 2021). "A better understanding of these issues will further reveal the molecular mechanism underlying the action of TCF7L2 in atherosclerosis, which is necessary for the development of new anti-atherosclerotic drugs in the future." (PMID 34568447, 2021). "In this review, we summarize the anti-atherosclerosis effect and novel mechanisms underlying the function of TCF7L2 to elucidate its potential as an anti-atherosclerosis biomarker and provide a novel therapeutic target for cardiovascular diseases." (PMID 34568447, 2021). "Understanding the mechanisms underlying the recruitment of VSMCs by TCF7L2 may provide novel insights into the pathogenesis of atherosclerosis." (PMID 34568447, 2021). "On the one hand, TCF7L2 rs7903146 induces the development of T2D by damaging pancreatic β-cell function and stimulating IR, which causes the vascular endothelium to be more accessible to atherosclerosis." (PMID 34568447, 2021). "Many gene polymorphisms have been confirmed to be involved in the development of atherosclerosis, such as rs7903146 in TCF7L2." (PMID 34568447, 2021). "Considering TCF7L2 to be a determinant element of Wnt signaling, we will further explore the role of TCF7L2 in metabolism, inflammation, and atherosclerosis." (PMID 34568447, 2021). "In addition to metabolism, TCF7L2 can influence cell fate to alleviate atherosclerosis in the vascular endothelium." (PMID 34568447, 2021). "Therefore, in this review, we summarize the structure, function, and anti-atherosclerosis effects of TCF7L2 in order to provide insight for the development of an alternative treatment strategy for CVD." (PMID 34568447, 2021). "Furthermore, TCF7L2 is a promising therapeutic target; we have provided a detailed description of its role in atherosclerosis from metabolism and inflammation to neointimal hyperplasia, which makes it suitable for clinical applications." (PMID 34568447, 2021). "Above all, TCF7L2 rs7903146 appears to have an intricate relationship with atherosclerosis." (PMID 34568447, 2021). "Therefore, we think the preservation of TCF7L2 level in the arterial cells would be very important for the prevention and/or protection of atherosclerosis." (PMID 30006590, 2018). "TCF7L2 is a downstream transcription factor in the canonical Wnt/β-catenin pathway, and it has been shown to be involved in insulin synthesis, vascular cell proliferation, inflammation, and plaque formation, all of which are key processes in atherosclerosis 39,58." (PMID 40303486, 2025). "Therefore, it is possible that preservation of TCF7L2 expression could lead to reduce the atherosclerosis through the increase of GLP-1 receptor expression and decrease of inflammation process, although further evaluation would be necessary to demonstrate this point." (PMID 30006590, 2018).
colorectal tumors (8 papers, 2017 to 2025). "The analysis revealed that tumors harboring ESR1 mutations exhibited significantly elevated transcriptional activity of ESR1, while colorectal tumors carrying TCF7L2 mutations showed decreased transcriptional activity of TCF7L2." (PMID 41390696, 2025). "Unrestrained transcriptional activity of β-CATENIN and its binding partner TCF7L2 frequently underlies colorectal tumor initiation and is considered an obligatory oncogenic driver throughout intestinal carcinogenesis." (PMID 36609428, 2023). "Thus, it is possible that colorectal tumors retaining one functional allele or expressing mutant TCF7L2 protein variants exhibit phenotypes different from TCF7L2KO and TCF7L2KOΔE6 cells." (PMID 32203164, 2020). "Despite its negative impact on cell cycle progression, TCF7L2 loss-of-function may thereby increase malignancy, which could explain why TCF7L2 is mutated in a sizeable fraction of colorectal tumors." (PMID 32203164, 2020). "Thus, the frequency of TCF7L2 mutations/copy number loss are positively correlated with increased tissue invasion and metastasis which is consistent with a migration and invasion suppressor role for TCF7L2 in colorectal tumors." (PMID 32203164, 2020). "Further, also complete independence of CRC cells from WNT/β-CATENIN pathway activity was reported which likewise would explain why a subset of human colorectal tumors and CRC cell lines can tolerate the loss of TCF7L2." (PMID 36609428, 2023). "Interestingly, cluster 11 also showed very low expression of the Tcf7l2 gene in cells isolated from colorectal tumors." (PMID 40221753, 2025). "These agents may show potential as therapeutic interventions to reduce the contribution of shared TCF7L2/AP-1 target genes to colorectal tumor progression." (PMID 30131849, 2018). "Considering the production of the differentiated epithelial cell marker Krt20, it could be concluded that a method mimicking the suppression of Tcf7l2 expression (inhibition of the Wnt pathway) could be a therapeutic approach to the treatment of colorectal tumors." (PMID 40221753, 2025).
glioma (8 papers, 2013 to 2024). A benign or malignant brain and spinal cord tumor that arises from glial cells (astrocytes, oligodendrocytes, ependymal cells). "In our study, we performed a preliminary analysis between the expression level of TCF7L2 and overall survival risk of glioma among Chinese people." (PMID 34305772, 2021). "A VTI1A variant is associated with the risk of glioma, and the fusion product of the VTI1A gene and the adjacent TCF7L2 gene is involved in glioma development." (PMID 35711736, 2022). "We measured TCF7L2 expression levels in 97 patients with glioma by qRT-PCR." (PMID 34305772, 2021). "The TCF7L2 expression and prognostic value in glioma have rarely been reported." (PMID 34305772, 2021). "We focused on the TCF7L2 effect and the expression level in glioma tissue." (PMID 34305772, 2021). "TCF7L2 could be a potential prognostic factor and therapeutic target for patients with glioma." (PMID 34305772, 2021). "Therefore, the aim of our study was to analyze the clinical value of TCF7L2 in glioma." (PMID 34305772, 2021). "Several genes down-regulated in BAT such as PRDM2, TCF7L2, RB1CC1, ATP2A2 are involved in the pathogenesis of other type of cancers, but not in gliomas." (PMID 23472076, 2013).
melanoma (8 papers, 2013 to 2025). A malignant, usually aggressive tumor composed of atypical, neoplastic melanocytes. "Herein, we show that SPARC expression in melanoma cells relies on transcriptional activation by PRRX1/TCF7L2-Sp1 and post-transcriptional regulation by miR-29b1~a." (PMID 40943659, 2025). "LEF1 is preferentially expressed by differentiated and proliferative cells, whereas TCF7L2 is mostly expressed by undifferentiated and invasive melanoma cells, and is inversely correlated with the expression of LEF1." (PMID 40943659, 2025). "In conclusion, the study highlights the role of the PRRX1/TCF7L2-Sp1/miR-29b1~a signaling axis in regulating SPARC expression in melanoma." (PMID 40943659, 2025). "Taken together, SPARC expression in melanoma cells relies on transcriptional activation by PRRX1/TCF7L2-Sp1 and is modulated through miR-29b1~a, which provides fine-tuning regulation over the switch between phenotypic states." (PMID 40943659, 2025). "LEF1 and TCF7L2 are both co-factors of β-catenin and are phenotype-specific in melanoma." (PMID 40943659, 2025). "Keeping in mind that phenotype switching in melanoma cells entails the exclusive expression of β-catenin cofactors LEF1 or TCF7L2, we interrogated whether SPARC can be integrated into this process, either in the presence or absence of PRRX1 expression." (PMID 40943659, 2025). "In melanoma, TCF7L2 regulates the expression of NEDD9 through miRNA to affect tumor progression." (PMID 39060928, 2024). "Since the in silico analysis indicated the presence of LEF/TCF (T cell factor/Lymphoid Enhancer factor)-binding sites “A/T A/T CAAAG” within the SPARC proximal promoter, we explored whether endogenous LEF1 or TCF7L2 TFs could bind to this promoter region in melanoma cells." (PMID 40943659, 2025). "Hence, although further research is needed, we speculate that PRRX1 and the activation of β-catenin/TCF7L2 may regulate the maximal activation of the SPARC promoter in melanoma cells, and maybe that of other mesenchymal genes." (PMID 40943659, 2025). "In this study, we propose a PRRX1/TCF7L2-Sp1/miR-29 regulatory axis, which involve Wnt/β-catenin and MAPK signaling pathways to regulate SPARC expression in melanoma." (PMID 40943659, 2025). "Its action is accompanied by an increase in TCF7L2, a cofactor of β-catenin, which was also found to be enriched in the SPARC promoter in invasive melanoma cells." (PMID 40943659, 2025). "In conclusion, we propose a PRRX1/TCF7L2-Sp1/miR-29 regulatory axis, which involves Wnt/β-catenin and MAPK signaling pathways, as a key mechanism controlling SPARC expression in melanoma." (PMID 40943659, 2025). "To this end, we first performed chromatin immunoprecipitation and found that TCF7L2 was significantly enriched in the SPARC promoter region (−175 to −25 nt relative to the TIS) in several melanoma cell lines tested, whereas LEF1 was not." (PMID 40943659, 2025).
type 1 diabetes (8 papers, 2007 to 2025). "TCF7L2 rs7903146 is also associated with type I diabetes mellitus and a singlet islet autoantibody positivity supporting that non-autoimmune pathways are involved in a subset of autoimmune type I diabetes." (PMID 38384655, 2024). "This study aimed to investigate the possibility of genetic association between TCF7L2 and type 1 diabetes (T1D)." (PMID 17683561, 2007). "Interestingly, TCF7L2 gene polymorphisms are linked to type 1 diabetes and T2D." (PMID 33865372, 2021). "Because of the effects on blood glucose homeostasis, the TCF7L2 gene variation may also be important in type 1 diabetes (T1D)." (PMID 17683561, 2007).
depression (7 papers, 2020 to 2025). "Intriguingly, genetic variations in the Tcf7l2 gene have been linked to an increased risk of type 2 diabetes, a metabolic disorder often co-occurring with depression." (PMID 39596468, 2024). "The results of our study elucidate the critical role of TCF7L2 in the LHb in modulating depressive-like behaviors in mice, providing novel insights into the molecular mechanisms underlying depression." (PMID 39596468, 2024). "Our study not only deepens our understanding of the neurobiological basis of depression but also highlights the therapeutic potential of targeting TCF7L2 signaling in the LHb." (PMID 39596468, 2024). "The identification of TCF7L2 as a key modulator of depressive-like behaviors in the LHb offers new therapeutic avenues for depression." (PMID 39596468, 2024). "The CMS paradigm, widely used to model depression in rodents, led to a significant reduction in TCF7L2 in the LHb neurons of the mice." (PMID 39596468, 2024). "Targeting TCF7L2 or its downstream signaling pathways could be a novel strategy for treating depression." (PMID 39596468, 2024). "however, miR-22-3p was not influenced via depression of TCF7L2." (PMID 34753394, 2022).
autism (6 papers, 2016 to 2025). Persistent deficits in social interaction and communication and interaction as well as a markedly restricted repertoire of activity and interest as well as repetitive patterns of behavior. "To observe social behavior in Tcf7l2 cKO mice compared with their littermate controls, we used a naturalistic setting that was recently developed and tested in mouse models of autism (schematic)." (PMID 37798419, 2024). "Among the autism risk genes, those involved in transcriptional regulation, such as RNASE1 and TCF7L2, are predominantly expressed in the early stages of this lineage." (PMID 39363111, 2024). "The Wnt signaling pathway (GO:0016055) mediated by TCF7L2 was significantly enriched in this lineage (FDR = 4.79 × 10−2), suggesting its involvement in the pathophysiology of autism and developmental delay." (PMID 39363111, 2024).
cervical carcinoma (6 papers, 2018 to 2026). A carcinoma arising from either the exocervical squamous epithelium or the endocervical glandular epithelium. "It activates a novel β-catenin/TCF7L2/LGR6-positive feedback loop in LGR6high cervical cancer stem cells (CSCs) to enhance the properties of cancer stem cells, including self-renewal, differentiation, and tumorigenicity." (PMID 38670944, 2024). "In further studies, western blot and RT-PCR demonstrated that overexpression of TCF7L2 upregulated LGR6 expression in cervical cancer cells at both the protein and mRNA levels, implying that TCF7L2 and β-catenin (CTNNB1) are upstream regulators of LGR6." (PMID 34489551, 2021). "Second, by analyzing the TCGA database and our clinical specimens, we found that LGR6 was positively correlated with TCF7L2 in cervical cancer." (PMID 34489551, 2021). "This is the first study to confirm that the existence of a novel β-catenin/TCF7L2/LGR6-positive feedback loop in cervical cancer, and LGR6 induces its own expression via the β-catenin/TCF7L2/LGR6 loop to further activate the Wnt signaling." (PMID 34489551, 2021). "In cervical cancer, miR-212 inhibited the proliferation and metastasis of cervical cancer cells by inhibiting TCF7L2." (PMID 34348712, 2021). "We proved that the Wnt agonist CHIR-99021 and overexpression of CTNNB1 could upregulate the expression of TCF7L2 in cervical cancer cells and 293T cells." (PMID 34489551, 2021). "Furthermore, as TCF7L2 expression increased, the probability of cervical cancer patients’ RFS decreased (p = 0.0054)." (PMID 34489551, 2021). "Consistent with LGR6, TCF7L2 also predicted a poor prognosis in cervical cancer." (PMID 34489551, 2021). "Thus, our study demonstrated that LGR6 activated a novel β-catenin/TCF7L2/LGR6-positive feedback loop in LGR6high cervical cancer stem cells (CSCs), which provided a new therapeutic strategy for targeting cervical CSCs to improve the prognosis of cervical cancer patients." (PMID 34489551, 2021). "Furthermore, TCF7L2 was also upregulated in LGR6high cervical cancer cells." (PMID 34489551, 2021). "Then, we tested LGR6, β-catenin, TCF7L2, c-Myc, OCT4, and SOX2 in 15 cervical cancer tissues by IHC." (PMID 34489551, 2021). "Furthermore, we used western blotting to detect LGR6, β-catenin, TCF7L2, c-Myc, and SOX2 in 16 cervical cancer samples." (PMID 34489551, 2021). "Interestingly, consistent with LGR6, TCF7L2, CTNNB1, MYC, and POU5F1 were all related to the poor prognosis of cervical cancer." (PMID 34489551, 2021).
diabetic nephropathy (6 papers, 2014 to 2025). "In our study the T allele of the rs7903146 SNP in the TCF7L2 gene confers the risk of developing diabetic nephropathy." (PMID 24574000, 2014). "In conclusion, the findings of our study show that the T allele of the rs7903146 SNP in the TCF7L2 gene confers the risk of developing diabetic nephropathy." (PMID 24574000, 2014). "TCF7L2 is a key transcriptional effector molecule of the Wnt signalling pathway, which can affect diabetic nephropathy by regulating the expression of VEGFA." (PMID 35846885, 2022). "TCF7L2 is related with T2DM risk and DM complications such as diabetic nephropathy, and is also a susceptibility locus for CRC." (PMID 35893034, 2022). "Other studies propose GREM1 as an important mediator for diabetic kidney disease, and due to its interaction with TCF7L2, which facilitates its DNA binding, it can be considered one of the common genetic factors for T2DM and CRC." (PMID 35893034, 2022).
diabetic retinopathy (6 papers, 2010 to 2025). "Genetic factors associated with the development of diabetic retinopathy mutations or variations in genes involved in glucose and lipid metabolism, such as the gene for insulin (INS) or the transcription factor 7-like 2 (TCF7L2), have been associated with an increased risk of diabetic retinopathy." (PMID 38918766, 2024).
glioblastoma (6 papers, 2021 to 2024). The most malignant astrocytic tumor (WHO grade IV). "We established glioblastoma (GBM) cell lines expressing ectopic TCF4N, an isoform of the β‐catenin interacting transcription factor TCF7L2, and evaluated its functions in GBM tumorigenesis and chemotherapy in vitro and in vivo." (PMID 36116131, 2022).